TNF (tumor necrosis factor)
Diseases named in the same sentence as TNF in open-access papers (continued):
Sharing a sentence is not in itself a finding about the gene and the disease.
depression (continued). "Clinical studies have found that compared with normal people, patients with depression have proinflammatory cytokines such as tumor necrosis factor-α(TNF-α)、Interleukin-1β(IL-1β)、IL-6 and interferon While anti-inflammatory cytokines such as IL-10, IL-4, IL-8 and transforming growth factor." (PMID 37167313, 2023). "Meta-analyses on biomarkers of depression in nonpregnant individuals repeatedly highlight the importance of TNF-α as a diagnostic marker as well as a marker of treatment response." (PMID 37892657, 2023). "Furthermore, isorhamnetin and similar flavonols have been found to normalize proinflammatory cytokines such as TNF-α and IL-1β in both the periphery and the brain of experimental animals or plasma samples from patients diagnosed with depression." (PMID 37754268, 2023). "Subsequently, anxiety- and depression-like behaviors and spatial learning and memory function were evaluated in the offspring, as were the hippocampal levels of markers of inflammation (IL-1β, IL-6, TNF-α) and synaptic function (PSD-95, SYN)." (PMID 37560531, 2023). "Several inflammatory markers, namely IL-1, IL-6, TNF-α, and hsCRP, have been found to be elevated in individuals with depression, and thus depression may be pathophysiologically underpinned by chronic inflammation." (PMID 37163324, 2023). "The authors did not confirm any association between TNF-α level and depression, although the effect size fell short of statistical significance, which was coherent with a trend observed in the previous meta-analysis." (PMID 34590201, 2023). "Recently, some studies shed some light on the potential mechanism of action of TNF-α in depression." (PMID 37967104, 2023). "This oxidative stress and increased depression lead to demyelination and cerebral atrophy, accompanied by elevated concentrations of inflammatory mediators such as tumor necrosis factor (TNFα) and specifically interleukin IL-6, along with IL-1α and IL-1β, in the serum and CSF." (PMID 37693246, 2023). "Here, we show that miR-146a levels are also downregulated in the PBMCs of depression patients, which may partially explain the observed increase of TNF-α levels." (PMID 37575572, 2023). "Notably the higher the circulating basal TNF-α levels the greater the effects of PA on reducing the depression." (PMID 36949894, 2023). "The development of depression is often accompanied by an increased inflammatory response, which increases levels of peripheral and central pro-inflammatory cytokines, including interleukin-1β (IL-1β), interleukin-6 (IL-6), and tumor necrosis factor-α (TNF-α)." (PMID 38094892, 2023). "Herein, TNF-α was associated with CESD-R, a questionnaire for evaluating depression." (PMID 37529617, 2023). "Indeed, type-2-diabetes-induced depression was accompanied by an increase in pro-inflammatory cytokines, including TNF-α, and a reduction in the BDNF content in the hippocampus." (PMID 37892186, 2023). "Although TNF-α, IL-6, and IL-1β play crucial roles as acute phase proteins, they may act differently in the pathology of depression." (PMID 37009013, 2023). "The current observation in our study that LAT reduces CSDS-induced increase in IL-6 and TNF-α, concomitant with the mitigation of depression-like behavior, strongly supports this hypothesis." (PMID 37400661, 2023). "Direct and indirect effects between gratitude and depression through perceived stress and TNF-α." (PMID 37213708, 2023). "Of note, anti-TNF biologics have been proposed to alleviate both RA and depression symptoms; however, their prescription is approved only in severe cases of RA, and not all patients respond to them, thereby necessitating the frequent prescription of additional antidepressants." (PMID 37014697, 2023). "TNF-α has been shown to play a key role in the pathophysiology of depression." (PMID 37049434, 2023).
depression (continued). "During chronic mild stress, activation of microglial NLRP3 inflammasome triggers the release of A1 cocktail (TNF-α, IL-1α and C1q) to induce the production of A1-like astrocytes in hippocampus, which begins preceding to the onset of dendritic dysfunction and depression-like behaviors." (PMID 37794488, 2023). "Additionally, pro-inflammatory mediators such as macrophage inflammatory protein-2 (MIP2), IL-1β, iNOS, and TNF-α activate M1 microglia, which then produce many more damaging factors that reduce hippocampal neurogenesis and induce depression." (PMID 37881439, 2023). "Although classic inflammatory markers such as CRP, IL-6, and TNF-α are associated with depression and vitamin D deficiency, they do not seem to be all the mediators of this link." (PMID 37049606, 2023). "This hypothesis was supported by meta-analyses showing that cytokine concentrations, including IL6, IL1β, IL17, and TNFα, were raised in the peripheral blood of patients with depression and anxiety compared with healthy controls." (PMID 37916198, 2023). "Similarly, intercellular adhesion molecule-1 (ICAM-1), interleukin (IL)-1β, IL-6, IL-10, and tumor necrosis factor (TNF)-α are significantly increased in depression and bipolar disorder, while interferon (IFN)-γ is significantly decreased." (PMID 37628746, 2023). "Depressive symptoms and major depression were associated with elevated levels of inflammatory biomarkers such as C-reactive protein (CRP), interleukin (IL)-1, IL-6, tumor necrosis factor-alpha (TNF-α) and monocyte chemoattractant protein-1 (MCP-1)." (PMID 36915045, 2023). "Influenza virus infection might result in depression or suppression of cellular responses to reduce TNF-α." (PMID 37630849, 2023). "In this context, NF-κB has been hypothesized to stimulate the release of inflammatory mediators, including TNF-α, interleukin (IL)-1β, and IL-6, as well as promoting neuroinflammatory processes, finally leading to depression." (PMID 37998350, 2023). "Therefore, more careful studies need to be done to determine the role of TNF and IL6 in endometriosis-associated central sensitization, anxiety, and depression." (PMID 36879305, 2023). "Serum levels of TNFα have been positively associated with tinnitus loudness, stress, and depression in some studies, but not others." (PMID 36902722, 2023). "Furthermore, the antidepressant effects of MLT were found to be related to the modulation of neuroinflammation by regulating hippocampal NF-κB phosphorylation and cytokines (TNFα, IL-1β, and IL-6) in the LPS-induced depression model." (PMID 36747075, 2023). "Interestingly, the first paper that reported increased TNF-α in major depression, found that the serum levels of this cytokine were higher in major depression than in MS." (PMID 37509005, 2023). "At the cellular level, repercussions of these processes could be the production of IL-1α, IL-1β, TNF-α, and IL-6, as well as the activation of microglia and the impairment of astrocytes in depression." (PMID 36899845, 2023). "Moreover, a scoring scheme was constructed to quantify the IBD-related depression gene signature and anticipate the therapeutic outcome of patients to anti-TNF-alpha medication." (PMID 36923403, 2023). "These authors also found that IL-1β and TNF-α may be related with moderate depression symptoms in early pregnancy to midgestation." (PMID 37239199, 2023). "Direct and indirect effects between gratitude and depression through social support and TNF-α." (PMID 37213708, 2023). "In line with what was observed in plasma, TNF-α mRNA levels were found upregulated in depression patients compared with healthy controls, suggesting that PBMCs might be contributing to the observed increased levels in plasma." (PMID 37575572, 2023). "We also used multivariate-adjusted models to investigate whether anxiety/depression symptoms were associated with the efficacy of AZA/6-MP and anti-TNF agents." (PMID 37547213, 2023).
depression (continued). "In the present study, we found that maternal separation led to anxiety- and depression-like behaviors in offspring, the upregulation of the hippocampal levels of pro-inflammatory cytokines (IL-1β, IL-6, and TNF-α), and the inhibition of the Sirt1/NF-κB signaling pathway." (PMID 37273278, 2023). "Following the discovery of the D. score’s strong correlation with the immune-inflammatory response, we tested the hypothesis that the genetic signature of depression may be used to predict patients’ responses to anti-TNF-alpha therapies." (PMID 36923403, 2023). "Patients with depression exhibit an increased expression of proinflammatory cytokines and their receptors in the peripheral blood and cerebrospinal fluid (CSF), especially IL-1β, IL-6 and TNF-α, as the cardinal feature of the inflammatory responses." (PMID 36838809, 2023). "They found that Infliximab, a TNF-α inhibitor, reduced the level of anhedonia, suggesting that inflammation may play an important role in depression." (PMID 37891859, 2023). "Moreover, TNF and IL6 in the brain are also implicated in depression and anxiety-like behavior in mice." (PMID 36879305, 2023). "An experimental animal study showed that the improvement of depression-like behavior by FMT may be associated with an increase in 5-HT levels and decreases in IL-1β and TNF-α levels." (PMID 38057705, 2023). "Plausibly, increased CRP and fibrinogen predicted heightened depression components, particularly somatic symptoms, by producing more proinflammatory cytokines from peripheral blood mononuclear cells (e.g. IL-6, tumor necrosis factor-α) (Haroon, Raison, & Miller, 2012)." (PMID 35924730, 2023). "The cause of depression like behavior development may be attributed to inflammation-based theory of depression as hippocampal levels of IFN-γ and TNF–α were significantly increased in mice which received transplant." (PMID 36978872, 2023). "MSD has been found to activate the microglial cells and increase the expression levels of proinflammatory cytokines, including interleukin (IL)-1β, IL-6, and tumor necrosis factor-alpha (TNF-α), in the hippocampus, accompanied by depression and cognitive impairment." (PMID 37168717, 2023). "Astrocytic TNF-α signalling is also reported to affect cognitive function which may be of relevance to multiple sclerosis, Alzheimer’s disease, and depression." (PMID 37457896, 2023). "At present, the most consistent conclusion regarding the relationship between neuroinflammation and depression is that levels of proinflammatory cytokines; including TNF-α, IL-1β, and IL-6; are increased in both the plasma and central nervous system in patients suffering from MDD." (PMID 36909192, 2023). "This study endeavors to shed light on the utility of TNF-α and MCP-4 as potential biomarkers for MDD, advancing our understanding of the complex interplay between immune dysregulation and depressive disorders and offering promising insights into improved diagnostic and therapeutic approaches." (PMID 37967104, 2023). "Patients with depression disorder exhibit a chronic inflammatory state which is characterized by elevated serum levels of pro-inflammatory cytokines, including TNF-α, IL-1β, IL-2, IL-6, IL-12, and decreased levels of anti-inflammatory cytokines, such as IL-10, compared to controls." (PMID 37273278, 2023). "The current study suggested that both TNF-α (-308G/A) and HHV-6 might affect TNF-α, IL-6, and IL-10 expression, influencing the severity and progression of depression via inflammatory processes." (PMID 37766304, 2023). "Additionally, multivariate logistic regression analyses disclosed that TNF‐α (both P < 0.05) and IL‐1β (both P < 0.001) were independently correlated with increased anxiety and depression risks in NSCLC survivors." (PMID 34697903, 2022).
depression (continued). "In the chronic inflammatory state associated with stress, Interleukin (IL)-1beta, Tumor Necrosis Factor (TNF)-alpha and IL-6 have been reported to be the most represented cytokines; Serum C-Reactive Protein, IL-1 and IL-6 were the most prevalent in depression." (PMID 35323251, 2022). "For example, arthritis, as a chronic inflammatory disease, can increase the expression of major proinflammatory cytokines, such as tumor necrosis factor-α, interleukin-6 and interleukin-1β, which, through the brain, affect pathophysiological and neurotransmitter functions relevant to depression." (PMID 36203679, 2022). "Periodontal pathogen endotoxins are associated with elevated inflammatory parameters and proinflammatory cytokines (especially TNF α and IL‐6) that may potentiate the inflammation and increase vulnerability to depression." (PMID 34729949, 2022). "Proinflammatory cytokines, such as IL-1β, IL-6, and TNF-α, might play crucial roles in the pathophysiology and treatment of depression." (PMID 35496318, 2022). "Studies also suggest that physical activity may promote mental health by decreasing anxiety and depression symptoms through downregulating TNF-α." (PMID 35873235, 2022). "Individuals suffering from depression have elevated levels of pro-inflammatory cytokines, such as tumor necrosis factor alpha (TNF-α) and interleukin-6 (IL-6), but also other mediators, such as chemokines, and this seems to contribute to the onset of this disease." (PMID 35216147, 2022). "Cytokines IL-6 and TNF-α appeared to be good predictors for depression." (PMID 35757220, 2022). "Various studies demonstrate that, e.g., schizophrenia, depression, suicidal ideation and post-traumatic stress disorder are characterized with increased levels of inflammatory markers, particularly IL-1β, IL-2R, IL-6, IL-17A, TNF-α and CRP." (PMID 35682824, 2022). "Therefore, after adjusting covariates by multivariate logistic regression analyses, only TNF‐α and IL‐1β were independently correlated with increased anxiety and depression risks in NSCLC survivors." (PMID 34697903, 2022). "Amycenone, a proprietary mixture of compounds which are present in the fruiting body of H. erinaceus, demonstrated anti-inflammatory activity against cytokines TNF and IL and reduced inflammatory induced depression in test animals a similar activity observed with SSRIs and SNRIs." (PMID 35330292, 2022). "Specifically, microglia, the immune cells of the nervous system, are activated during neuroinflammation triggered by depression, resulting in the overexpression of various pro-inflammatory mediators, including tumor necrosis factor-α (TNF-α), interleukin-6 (IL-6) and NO, among others." (PMID 36330352, 2022). "In the setting of human depression, correlations between adipose tissue mass and inflammation have been much less studied, assessment of inflammatory markers was limited to measures of IL-6 and TNF–α and findings to date are somewhat contradictory." (PMID 35444568, 2022). "High IL-1β (P=0.011, adjusted P=0.044), IL-6 (P=0.010, adjusted P=0.040), and IL-17 (P=0.011, P=0.044 after adjustment), but not TNF-α (P=0.104, P=0.416 after adjustment), were associated with depression occurrence." (PMID 35239774, 2022). "Furthermore, the proinflammatory cytokines TNF-α, IL-1β, and IL-6 have been reported to be raised in rodents that exhibited a depression-like phenotype." (PMID 35939172, 2022). "Risperidone, interacting with TNF, as an adjunctive therapy for treatment-resistant depression, may improve rate of response and remission based on clinical evidence." (PMID 34997195, 2022). "In addition, the POWER study demonstrated a strong correlation between patients with major depressive disorder and the IL-6 and TNF-α sweat levels." (PMID 36556392, 2022). "Compared with those who do not respond to anti-TNF treatment, those who do respond to it take a lower risk of depression." (PMID 36755665, 2022).
depression (continued). "Proinflammatory cytokines (IL-1β, IL-6 and TNF-α) may be screening biomarkers in the prediction of treatment response in patients with depression." (PMID 36350802, 2022). "Interestingly, BDNF emerged among the genes shared by depression and atherothrombosis, and it was well-connected to all the genes identified in both databases, namely, IL-1β, IL-6, IL-18, TNF, APOE, ACE, MTR, MTHFR genes." (PMID 35911513, 2022). "Hypotheses such as ‘macrophage theory of depression’ and the ‘cytokine hypothesis of depression’ were proposed to describe a higher expression of IL-1, TNF‐α, IL-6, and IL-8 in patients suffering from depression." (PMID 35784295, 2022). "In addition, genetic polymorphisms in inflammatory factors (e.g. IL-1β, TNF, and CRP) are strongly associated with depression and treatment outcomes." (PMID 36186850, 2022). "Increased serum TNF-α levels positively correlate with increased anxiety and/or depression." (PMID 35053845, 2022). "TNF is an important cytokine contributing to the inflammatory hypothesis of depression, has an important function in the pathophysiology of depression, and represents a potential marker of depression." (PMID 35770096, 2022). "Furthermore, serum corticosterone levels were markedly increased with IL-1β injection, while GR inhibitor RU486 reduced IL-1β-induced depression-like behavior and TNF-α and IL-6 expression." (PMID 36232376, 2022). "Moreover, among the detected inflammatory cytokines, IL-6 showed to be the most effective screening tool to predict depression, with an AUC of 0.76, a sensitivity of 79.3%, and a specificity of 67.7%, followed by TNF-α with an AUC of 0.75." (PMID 35757220, 2022). "Hence, serum TNF‐α, IL‐1β, IL‐6, and IL‐17 were positively related to anxiety and depression in NSCLC survivors." (PMID 34697903, 2022). "The activation of the inflammatory response system during stress exposure is associated with hypothalamic–pituitary–adrenal axis (HPA) hyperactivity, indicating that HPA hyperactivity in depression is contributed by proinflammatory cytokines, such as IL-1β and TNFα." (PMID 35328018, 2022). "Based on the evidence in younger patients with depression, we hypothesized that depressed geriatric patients had elevated levels of IL-6, IL-8 and TNF-α compared to controls." (PMID 36172507, 2022). "Moreover, IL-6, QUIN, TNF, and KYN showed strong individual accuracy in predicting depression risk and severity at future timepoints, with the best performance using the 2nd trimester markers to predict symptoms emerging in the 3rd trimester." (PMID 35078975, 2022). "Higher levels of TNF-α and IL-6 have been found in the blood of patients with depression." (PMID 35573384, 2022). "From the perspective of the mechanism, it has been assumed that the increased production of TNF-α may play a pathogenic role in depression, and the TNF-α levels of patients with depression vary greatly in many clinical studies." (PMID 35722555, 2022). "Finally, studies show that Rb1 can prevent CRS-induced depression in mice because it inhibits the protein expression of IL-1β and TNF-α in BV-2 microglia induced by LPS." (PMID 35795547, 2022). "Earlier studies also confirmed a strong relationship between depression and an increase in Il-6 and TNF-α, but their increase, according to researchers, was similar regardless of whether it was the first depressive episode or a subsequent one." (PMID 35407663, 2022). "Occasionally, in diseases such as inflammatory bowel diseases, immunomodulating treatment (anti-TNF) can inadvertently help reduce the inflammatory-mediated depression and has been shown to reduce symptoms even after adjusting for the anxiety associated with the condition." (PMID 35267893, 2022). "Moreover, Lacticaseibacillus paracasei NK112 exerted protective effects against Escherichia coli-induced depression through decreasing the expression of IL-1α, IL-6, and TNF-α, and inhibiting the activity of NF-κB in the hippocampus." (PMID 36358502, 2022).